TOMM20 (translocase of outer mitochondrial membrane 20)
Diseases named in the same sentence as TOMM20 in open-access papers (continued):
Sharing a sentence is not in itself a finding about the gene and the disease.
fibrosarcoma (1 paper, 2025). A malignant mesenchymal fibroblastic neoplasm affecting the soft tissue and bone. "Specifically, when TOMM20 is overexpressed in MCA‐205 fibrosarcoma cells, it leads to an upregulation of three members of the apoptosis inhibitory BCL2 family of proteins: BCL‐2, BCL‐xl, and A1/Bfl1." (PMID 39996379, 2025). "Next, we aimed to investigate the influence of TOMM20, along with exposure to lactate and glutamine, on mitochondrial oxidative phosphorylation (OXPHOS) metabolism by measuring the oxygen consumption rates (OCR) in both TOMM20 overexpressing or control EV fibrosarcoma cells." (PMID 39996379, 2025). "Therefore, we have demonstrated that TOMM20 in fibrosarcoma induces resistance to BCL‐2 inhibitor, and immune checkpoint inhibition but is sensitive to complex I inhibitor." (PMID 39996379, 2025). "Moreover, monocarboxylate transporters MCT1 and MCT4 were upregulated in TOMM20‐overexpressing fibrosarcoma cells." (PMID 39996379, 2025). "We observed higher expression of PD‐L1 on TOMM20‐overexpressing fibrosarcoma cells and tumors." (PMID 39996379, 2025). "However, MCT1 was upregulated, and MCT4 was downregulated in TOMM20 knockdown fibrosarcoma cells." (PMID 39996379, 2025).
hepatoma (1 paper, 2022). "The granular cytoplasmic SPOCK1 reaction raised the possibility that the proteoglycan localizes in the mitochondria; thus, double fluorescent immunostainings were carried out with SPOCK1 antibody together either with TOMM20 or mitochondrial marker (MitoTracker-red, M22425) on hepatoma cell lines." (PMID 35186754, 2022). "In hepatoma cell lines, the cytoplasmic SPOCK1 colocalized with mitochondrial markers, such as MitoTracker and TOMM20, a characteristic protein of the outer membrane of the mitochondrion and could be detected in the cell nucleus." (PMID 35186754, 2022).
Hypoglycemia (1 paper, 2022). A decreased concentration of glucose in the blood. "As we found in patients with DM, we observed the same reduced mean intensity of Cx43, colocalization in Cx43 and N-cadherin, and significant increase in Cx43 and Tomm20 colocalization in DCM mice, while acute hypoglycemia challenge can further intensify Cx43 translocation." (PMID 35369285, 2022).
injury (1 paper, 2022). Damage inflicted on the body as the direct or indirect result of an external force, with or without disruption of structural continuity. "Third, other mitochondrial dysfunction markers, such as oxidative stress and reduced mitochondrial biogenesis, were not assessed, though oxidative stress and TOMM20 have been reported to be implicated in hyperoxia-induced lung injury." (PMID 36552613, 2022).
ischemic stroke (1 paper, 2024). A stroke disorder caused by obstruction of blood flow to the brain, due to thrombotic (local blood clot formation) or embolic (due to a blood clot or other material traveling from another site) event. "However, TSG could promote the transfer of Parkin to mitochondria, which led to the downregulation of Tomm20 in mitochondria, indicating activation of PINK1/Parkin-mediated mitophagy might be implicated in the neuroprotection of TSG on ischemic stroke." (PMID 39406480, 2024).
lymphoid cancers (1 paper, 2025). "TOMM20 has previously been identified as being highly expressed in epithelial and lymphoid cancers and is a prognostic biomarker." (PMID 39996379, 2025).
metabolic syndrome (1 paper, 2016). A cluster of metabolic risk factors for CARDIOVASCULAR DISEASES and TYPE 2 DIABETES MELLITUS. "The TOMM20 gene was previously identified as differentially expressed and methylated between severely obese subjects with and without metabolic syndrome (MS)." (PMID 27478511, 2016).
myocardial infarction (1 paper, 2023). Gross necrosis of the myocardium, as a result of interruption of the blood supply to the area, as in coronary thrombosis. "Thereafter, the SVM-RFE algorithm, random forest algorithm, and LASSO algorithm were utilized to identify mitophagy genes associated with myocardial infarction, including ATG5, TOMM20, and MFN2." (PMID 37304955, 2023).
ovarian carcinoma (1 paper, 2024). A malignant neoplasm originating from the surface ovarian epithelium. "Through multicolor immunohistochemistry, we found that ovarian cancer cell-derived EVs increased colocalization of CD31 with LC3 and TOMM20 in primary tumor tissues of the orthotopic OC mouse model." (PMID 38468343, 2024).
rhabdomyolysis (1 paper, 2023). Necrosis or disintegration of skeletal muscle often followed by myoglobinuria. "Compared with the great loss in male mice, TOMM20 and PGC-1α were largely preserved in female mice in rhabdomyolysis-induced AKI model." (PMID 37185276, 2023).
sarcoma (1 paper, 2025). A usually aggressive malignant neoplasm of the soft tissue or bone. "TOMM20 induces sarcoma aggressiveness by increasing oxidative phosphorylation (OXPHOS), maintaining a reduced redox state, decreasing ROS, increasing migration, and enhancing resistance to apoptosis." (PMID 39996379, 2025). "Hence, we decided to investigate the impact of knocking down TOMM20 using CRISPR‐Cas9 in sarcoma cell lines and evaluate whether TOMM20 is essential for the expression of drivers of cancer aggressiveness." (PMID 39996379, 2025).
spinal cord tumors (1 paper, 2023). "Furthermore, overexpression of TOMM20 led to aggressiveness, resistance to treatment, and recurrence in spinal cord tumors, which was significantly associated with the prognosis of spinal cord tumors." (PMID 37405988, 2023).
triple-negative breast carcinoma (1 paper, 2025). An invasive breast carcinoma which is negative for expression of estrogen receptor (ER), progesterone receptor (PR), and human epidermal growth factor receptor 2 (HER2). "In triple-negative breast cancer, TGF-β1 induces a TOMM20-low phenotype, disrupting mitochondrial protein import and OXPHOS." (PMID 41429765, 2025).
tumor (45 papers, 2015 to 2025). "Monocarboxylate transporter (MCT) on the tumor cell membrane and the translocation enzyme TOMM20 on the mitochondrial membrane were reportedly associated with the prognosis of thyroid cancer." (PMID 31423225, 2019). "The loss of TOMM20 in PCa tumor specimens might become a useful predictor of PCa sensitivity to AR antagonists." (PMID 37563661, 2023). "In vivo, we showed that TOMM20 overexpression led to larger tumors, while TOMM20 knockdown reduced tumor size." (PMID 39996379, 2025). "To summarize, TOMM20 upregulation increased tumor size, enhanced the expression of drivers of cancer aggressiveness, and reduced tumor apoptosis." (PMID 39996379, 2025). "To summarize, suppressing TOMM20 decreased tumor growth, reduced oxygen consumption, and heightened extracellular acidification in tumor microtissues." (PMID 39996379, 2025). "One previous study showed that TOMM20 expression was sufficient to drive tumor growth and other studies have shown that TOMM20 expression is associated with cancer aggressiveness." (PMID 39996379, 2025). "Mice receiving MCA‐205 cells with TOMM20 knockdown had more than a 50% reduction in tumor size for both clones." (PMID 39996379, 2025). "We injected mice with MOC‐1 with TOMM20 overexpression and control EV cells and found that TOMM20 overexpression significantly increased tumor volume compared to control EV." (PMID 39996379, 2025). "Conversely, TOMM20 knockdown suppresses these effects, reducing tumor progression and OXPHOS in vivo." (PMID 39996379, 2025). "Immunofluorescence for Ki67, cleaved-caspase-3 and Tomm20 indicated decreased proliferation, increased apoptosis and elevated accumulation of mitochondria in tumor tissues treated with curcumin." (PMID 40163489, 2025). "We also observed that tumor weight was significantly reduced in the TOMM20 knockdown CH2879 cells compared to controls." (PMID 39996379, 2025). "To confirm our in vivo tumor study with an epithelial cancer cell line, we generated TOMM20 overexpressing MOC‐1 cells and verified via western blot analysis." (PMID 39996379, 2025). "Consistently, multicolor immunohistochemistry showed that the IDO1 inhibitor decreased the colocalization of CD31 with LC3 and TOMM20 in primary tumor tissues of the orthotopic OC mouse model." (PMID 38468343, 2024). "Consistently, immunohistochemistry in PARCB tumor sections showed increased mitochondrial content (TOMM20) and neuroendocrine (NCAM1) protein expression in PGC-1α-High tumors." (PMID 39589879, 2024). "The expression correlation of TOMM20 and AR in PCa was determined by analyzing publicly available datasets, or by IHC staining in tumor specimens." (PMID 37563661, 2023). "The tumor growth curve and comparison of tumor sizes at the endpoint of the experiment demonstrated that TOMM20 depletion promoted tumor growth and reduced the anti-tumor effect of Casodex." (PMID 37563661, 2023). "AR showed a high correlation with TOMM20 expression in the tumor specimens of PCa patients and PCa cells." (PMID 37563661, 2023). "We further examined the effects of TOMM20 depletion on the anti-tumor effect of Casodex in PCa xenografts." (PMID 37563661, 2023). "Studies have shown that TOMM20 expression directly affects mitochondrial function, including ATP production, membrane potential maintenance, and regulation of tumor cell activity such as S phase cell cycle and apoptosis." (PMID 37449209, 2023). "MCT4 is associated with glycolytic metabolism and oxidative stress, whereas MCT1 and TOMM20 are markers of tumor areas that are proliferative and mitochondria-rich." (PMID 35578327, 2022). "This indicated increased colocalization of LC3B and TOMM20 in PanNENs (n = 3) compared with control (n = 1) with TOMM20/LC3B overlap index being significantly higher in primary tumour tissue (p = 0.004)." (PMID 32114655, 2020).
tumor (continued). "Tumours from patients on metformin treatment had a significant increase in post-treatment TOMM20 expression, an IHC marker of mitochondrial mass." (PMID 31819173, 2020). "Our qualitative assessment of LC3B/TOMM20 and transmission electron microscopy findings in PanNENs, revealed strong mitophagy activity in these tumours, warranting further studies on mitophagy inhibition of pancreatic neuroendocrine neoplastic cells." (PMID 32114655, 2020). "All PTC thyrocytes from patients with and without advanced disease showed homogeneously high expression of TOMM20 throughout the tumor." (PMID 27213120, 2016). "In follicular adenoma specimens, all of the adenomatous thyrocytes demonstrated high expression of TOMM20 compared to adjacent non-tumor thyrocytes and nodular goiter samples." (PMID 27213120, 2016). "Additionally, we discovered that the immune checkpoint protein programmed death ligand 1 (PD‐L1) was upregulated in TOMM20‐overexpressing cells, which can promote tumor immune evasion." (PMID 39996379, 2025). "Since TOMM20 suppression reduces the cancer aggressiveness phenotype in MCA‐205 and CH2879 cells, we wanted to establish whether TOMM20 is necessary for tumor growth." (PMID 39996379, 2025). "Additionally, overexpression of TOMM20 can contribute to the development of drug resistance in tumor cells against immune‐based therapies, thus impacting tumor treatment." (PMID 38800967, 2024). "Additionally, in the tumor specimens of advanced PCa patients, we observed low TOMM20 but high NCAM1 expression in the AR negatve PCa cells." (PMID 37563661, 2023). "TOMM20 upregulation may provide tumor cells the ability to avoid immune surveillance and encourage the development of cancer." (PMID 37405988, 2023). "However, beyond our expectations, the ratio of xenograft formation significantly elevated from 1/12 to 5/12 for TOMM20-depleted LNCaP cells, and tumor sizes were remarkably increased." (PMID 37563661, 2023). "Nonetheless, the precise manner in which TOMM20 expression contributes to tumor development and progression remains unclear." (PMID 37304955, 2023). "Indeed, Cyclin-D, Cyclin-B1 and TOMM20 play a fundamental role in the progression of the tumor cell cycle." (PMID 33339392, 2020). "In all non-tumor thyroid tissue and multinodular goiter samples, TOMM20 expression was low." (PMID 27213120, 2016). "Additionally, further research is needed to explore whether targeting TOMM20 expression in tumors could effectively reduce cancer aggressiveness and suppress tumor growth." (PMID 39996379, 2025). "Also, TOMM20 induced cell growth and migration in vitro and promoted tumor growth in vivo." (PMID 39996379, 2025). "Furthermore, the TOMM20 can facilitate ROS-induced pyroptosis and PHB2 is associated with apoptosis, indicating the interaction and coexistence of different programmed cell death as tumor grows." (PMID 35692054, 2022). "In this study, we examined the impact of TOMM20 on OXPHOS, redox state, oxidative stress, cell growth, resistance to apoptosis, migration, and tumor growth." (PMID 39996379, 2025). "Tumors were cut, and tumor microtissues were created to determine the OCR and ECAR rates of the tumors from CH2879 TOMM20 knockdown tumors and control sgRNA ex vivo." (PMID 39996379, 2025). "TOMM20 overexpression in MCA‐205 cells increased antiapoptotic drivers and promoted cell survival, decreased ROS, increased NADH and NADPH levels, and tumor size." (PMID 39996379, 2025). "One possible explanation is that TOMM20 upregulated the CD8+ T cell, providing tumor-suppressive effect in our study based on TIMER analysis." (PMID 35692054, 2022). "Significant decrease in the relative expression of the mitochondrial genes Tomm20 and MT-ND1 was observed in tibialis anterior samples from tumour-bearing mice." (PMID 33975599, 2021).
tumor (continued). "Expression of Tomm20 and MT-ND1 was reduced in the tibialis anterior muscle of tumour-bearing mice, while the expression of COXIV and OPA1 was reduced in the gastrocnemius muscle of tumour-bearing mice." (PMID 33975599, 2021). "In another study on ATC, tumor tissues highly expressed both TOMM20 and MCT1 compared with non-tumor tissues, which was different from PTC (high expression of TOMM20 but low expression of MCT1)." (PMID 31423225, 2019). "TOMM20 expression is minimal in normal oral tissues but is detected at varying levels in most tumor cells, regardless of differentiation status." (PMID 40951345, 2025). "PCS inhibited the expression of TOMM20, and improved the expression of Bnip3, Cytoc as well as the conversion of LC3‐I to LC3‐II, which collectively emphasised the promotion of mitophagy in tumour‐conditioned RAW264.7 cells after PCS treatment." (PMID 40604335, 2025). "Similarly, another study using immunohistochemical analysis has shown that the markers of mitochondrial oxidative phosphorylation, such as TOMM20 and MCT1, are higher in HRS cells, but absent in TAM and tumor-associated lymphocytes." (PMID 30783096, 2019).
cancer (26 papers, 2015 to 2025). A tumor composed of atypical neoplastic, often pleomorphic cells that invade other tissues. "Translocase of outer mitochondrial membrane receptor 20 (TOMM20) is a mitochondrial receptor protein associated with cancer aggressiveness in many cancer subtypes, but the mechanisms remain poorly understood." (PMID 39996379, 2025). "Our laboratory previously showed that drivers of cancer aggressiveness were increased via the overexpression of TOMM20 in CH2879 cells." (PMID 39996379, 2025). "TOMM20 increases cancer aggressiveness by maintaining a reduced state with increased NADH and NADPH levels, oxidative phosphorylation (OXPHOS), and apoptosis resistance while reducing reactive oxygen species (ROS) levels." (PMID 39996379, 2025). "Elevated TOMM20 levels in CRC tissues are associated with cell cycle dysregulation, causing increased cell proliferation, as well as the invasiveness of cancer cells." (PMID 41154660, 2025). "TOMM20 is essential for the import of nuclear proteins, but its role in driving cancer aggressiveness remains poorly understood." (PMID 39996379, 2025). "In conclusion, TOMM20 is a driver of cancer aggressiveness by OXPHOS, apoptosis resistance, and the maintenance of a reduced state." (PMID 39996379, 2025). "In sum, TOMM20 overexpression increased cell viability, migration, and the expression of drivers of cancer aggressiveness in MCA‐205 cells." (PMID 39996379, 2025). "Genes such as PARP1, NAMPT, AIMP2, MCL1, and TOMM20 exhibited widespread amplifications of CNVs in multiple cancers, while genes like RNF146, GPX4, ESR1, CUL4A, and PTEN showed widespread deletions." (PMID 38499384, 2024). "We for the first time reported a novel mechanism by which the autophagic degradation of TOMM20 resulted in drug resistance to AR antagonists by promoting the acquisition of cancer stem-like cell characteristics." (PMID 37563661, 2023). "In HNSCC tumors, the poorly differentiated cancer cells are hyperproliferative (Ki-67+), mitochondrial-rich (TOMM20+/COX+) and use mitochondrial fuels (MCT1+)." (PMID 27213120, 2016). "Conversely, CRISPR‐Cas9 knockdown of TOMM20 alters these cancer‐aggressive traits." (PMID 39996379, 2025). "The fluorescence intensity of Tomm20 was elevated dose-dependently in cancer cells." (PMID 40163489, 2025). "This highlights the potential importance of TOMM20 in cancer aggressiveness." (PMID 39996379, 2025). "We found that TOMM20 overexpression led to increased cancer aggressiveness." (PMID 39996379, 2025). "Similarly, TOMM40L, a component of the TOM complex, likely supports cancer progression by enhancing mitochondrial function, akin to TOMM20's role in promoting cell proliferation, migration, and invasion in cancer." (PMID 39744494, 2025). "TOMM20 is highly correlated with the degree of malignancy of several cancer types, including PCa." (PMID 37563661, 2023). "Aberrant overexpression of TOMM20 has been reported in several cancer types." (PMID 37563661, 2023). "According to previous studies, upregulation of TOMM20 could be observed in many cancers such as hepatocarcinoma." (PMID 35692054, 2022). "However, the mechanisms by which TOMM20 drives cancer progression are poorly understood." (PMID 39996379, 2025). "Also, TOMM20 is highly expressed in many other human cancers and is a prognostic biomarker." (PMID 39996379, 2025). "TOMM20 overexpressing cells have higher maximum reserve capacity and can use lactate and glutamine as substrates for their increased OCR highlighting how cancer cells have high metabolic flexibility." (PMID 39996379, 2025). "Among the top 20 proteins, Drp1 (alias DNM1L), TOM20 (alias TOMM20), and VDAC1 differed significantly in cancer progression." (PMID 37198593, 2023). "When TOMM20 was depleted, the PCa cells underwent EMT, acquired the characteristics of cancer stem-like cells, and developed resistance to AR antagonists." (PMID 37563661, 2023).